RN7SL93P (RNA, 7SL, cytoplasmic 93, pseudogene)
Gene: Miscellaneous RNA gene on chromosome X (113,976,341 to 113,976,633, reverse strand). Ensembl gene ENSG00000240327.
Homologues: Orthologues: chimpanzee Metazoa_SRP (100% identical). Paralogues in human: RN7SL1 (77% identical), RN7SL3 (77% identical), RN7SL2 (76% identical), RN7SL664P (75% identical), RN7SL127P (75% identical), RN7SL220P (75% identical), RN7SL498P (75% identical), RN7SL239P (74% identical), RN7SL296P (74% identical), RN7SL63P (74% identical), RN7SL218P (74% identical), RN7SL378P (74% identical), and 704 more.